RNU1-57P (RNA, U1 small nuclear 57, pseudogene)
Gene: Small nuclear RNA gene on chromosome X (113,949,917 to 113,950,082, forward strand). Ensembl gene ENSG00000207220.
Homologues: Orthologues: chimpanzee U1 (100% identical), macaque U1 (96% identical), guinea pig U1 (67% identical), dog U1 (63% identical). Paralogues in human: RNU1-1 (80% identical), RNU1-2 (80% identical), RNU1-27P (80% identical), RNU1-28P (80% identical), RNU1-3 (80% identical), RNU1-4 (80% identical), RNVU1-18 (80% identical), RNVU1-29 (80% identical), RNVU1-31 (80% identical), U1 (80% identical), RNU1-148P (80% identical), RNVU1-28 (80% identical), and 133 more.